GSTP1 (glutathione S-transferase pi 1)
Diseases named in the same sentence as GSTP1 in open-access papers (continued):
Sharing a sentence is not in itself a finding about the gene and the disease.
breast carcinoma (continued). "GSTP1 promoter methylation has also been reported to be associated with a poor prognosis in breast cancer." (PMID 23226781, 2012). "Fisher’s exact test was used to determine the association between hypermethylation of the GSTP1 gene with the clinical stages of primary breast cancer patients." (PMID 23226781, 2012). "In the present study ER+/PR+ status was revealed to be significantly associated with GSTP1 methylation in breast cancer patients from northern parts of India." (PMID 23226781, 2012). "It has been reported that the deletion of the GSTM1 and GSTT1 gene as well as the variant allele of the GSTP1 rs1695 polymorphism impact overall breast cancer risk." (PMID 23226154, 2012). "Combined effect of all three GSTT1, GSTM1, and GSTP1 variants have been reported to have greater than a 3-fold increase in breast cancer risk compared with women with the common genotype for all three polymorphisms." (PMID 19440493, 2009). "Overall, the biomarkers notably constitute genes that participate in breast cancer related pathways (e.g. marker genes involved in estrogen receptor pathway) and genes that were previously implicated in other cancer types (e.g. GSTP1, FLT1)." (PMID 19458770, 2007). "Methyl-CpG-binding domain protein-2 (gene X99687) mediates transcriptional repression associated with hypermethylated GSTP1 CpG islands in MCF-7 breast cancer cells." (PMID 17316436, 2007). "In an earlier study of women receiving treatment for breast cancer, we found that low activity GSTP1 genotypes were associated with better survival, and these results were replicated in the Shanghai Breast Cancer Study." (PMID 16848913, 2006). "The GSTP1 313A>G mutation has been identified as an independent risk factor for neutropenic hematological toxicity resulting from anthracycline/taxane chemotherapy in breast cancer patients." (PMID 39598531, 2024). "Furthermore, the association of qualitative PMR of both genes (RARB + GSTP1) with breast cancer was estimated." (PMID 37548362, 2023). "On the other hand, GSTP1 methylation was associated with breast cancer." (PMID 37548362, 2023). "Meta-analysis of the association of GSTP1 polymorphism with risk of breast cancer." (PMID 32155154, 2020). "Consistent with the role of methylation of GSTP1 in the tumor’s progression, a study showed significantly increased gene methylation of GSTP1 in breast cancer cells, which was positively associated with tumor size and TNM stage, and negatively associated with the expression of ER/PR." (PMID 32334487, 2020). "Most investigations found a relationship between breast cancer and GSTP1 common polymorphisms." (PMID 32334487, 2020). "Our study showed that GSTP1-Ile105Val polymorphism could be a genetic risk factor for breast cancer." (PMID 32334487, 2020). "Some studies were investigating the association of the GSTP1 polymorphisms with breast cancer risk." (PMID 32334487, 2020). "A first study shows that GSTP1 Ile105Val polymorphism may be associated with an elevated breast cancer risk in the Asian population." (PMID 31357662, 2019). "Similarly, a large numbers of studies also comfirmed the role of GSTP1 in chemoresistance in breast cancer, overexpression of GSTP1 is linked to chemoresistance." (PMID 29116019, 2017). "Therefore, a systematic review and meta-analysis was conducted to evaluate the influence of the GSTP1 (A313G) polymorphism on treatment outcomes and toxicities in patients with breast cancer." (PMID 29069838, 2017). "Moreover, the silencing of GSTP1 gene expression induced by promoter methylation has been found to be implicated in the pathogenesis of breast cancer." (PMID 26585467, 2015). "Overall, the pooled results indicated that aberrant GSTP1 promoter methylation was significantly associated with the risk of breast cancer (OR = 7.85, 95 % CI = 5.12–12.01; Caucasians OR = 7.23, 95 % CI = 3.76–13.90 and Asians OR = 11.71, 95 % CI = 5.69–24.07)." (PMID 26585467, 2015).
breast carcinoma (continued). "Moreover, subgroup analyses were performed to identify the influence of abnormal GSTP1 promoter methylation on the risk of breast cancer." (PMID 26585467, 2015). "The results revealed that GSTP1 promoter methylation was closely associated with the risk of breast cancer in both Caucasians (OR = 7.23, 95 % CI = 3.76–13.90) and Asians (OR = 11.71, 95 % CI = 5.69–24.07), whereas, the correlation was stronger in Asians than in Caucasians." (PMID 26585467, 2015). "Following treatment with NAC and prior to surgery, serum samples obtained from 120 patients with stage II/III breast cancer were subjected to the OS-MSP assay for analysis of the glutathione S-transferase pi 1, Ras association (RalGDS/AF-6) domain family member 1 and retinoic acid receptor β2 genes." (PMID 24959284, 2014). "In a meta analysis it has been reported that individuals with GSTP1 Ile105/Val 105 genotype increase susceptibility to breast cancer in Asian population, while a good response and light toxicity were also observed in breast cancer patients carrying GSTP1 Ile105/Val 105 or Ile 105/Ile105 genotype." (PMID 25606397, 2014). "Individuals with GSTP1 Val/Val genotype had significantly better survival in hepatocellular carcinoma patients, but this genotype is associated with worse outcome in basal cell carcinoma and breast cancer." (PMID 25606397, 2014). "Thus, we conclude that the GSTP1 105Val allele increases breast cancer risk and aggressiveness and enhance response to CTX-based chemotherapy in women of North China." (PMID 23826324, 2013). "Furthermore, in vitro cellular experiments demonstrated that breast cancer cells with the GSTP1 105Val allele were significantly more sensitive to CTX-induced proliferation inhibition." (PMID 23826324, 2013). "Due to the limited number of cases with rare genotype Val/Val of GSTP1 lle105Val in this study, the preventive, diagnostic and therapeutic values of the genetyping for women and breast cancer patients should be further evaluated and confirmed by large multicenter studies." (PMID 23826324, 2013). "To determine whether the GSTP1 Ile105Val genotype is an independent factor associated with DFS in breast cancer patients, we performed multivariate analyses." (PMID 23826324, 2013). "The environmental pollution in developing countries such as China and India caused by increasing population levels and changes in modern lifestyle may contribute to the increased breast cancer risk in those with the GSTP1 105Val allele." (PMID 23826324, 2013). "In addition, we found that breast cancer patients with the GSTP1 105Val allele were more likely to bear a tumor with histological grade III, lymph node metastases, as well as ER negative than those carrying the Ile/Ile allele." (PMID 23826324, 2013). "Studies have been published concerning the potential effects of the changes to the activation and detoxification abilities of GST class π enzymes on an individual’s risk of breast cancer and have established an association between the GSTP1 Ile105Val polymorphism and breast cancer risk." (PMID 23226781, 2012). "Previously, we demonstrated that the GSTP1 polymorphism is associated with an increased risk of breast cancer and therefore, the current hypothesis was tested." (PMID 23226781, 2012). "High levels of GSTP1 have been associated with a poor prognosis in breast cancer." (PMID 23226781, 2012). "In summary, in this carefully designed and conducted study of genetic predictors of acute side effects from radiation therapy following lumpectomy for breast cancer, we found that women with GSTP1 genotypes encoding lower activity were more likely to experience toxicity of grade 2c and above." (PMID 16848913, 2006). "Methylation of the promoter region of GSTP1, a member of the glutathione S-transferases, which are a supergene family involved in the detoxification of carcinogens, is associated with gene inactivation in about 30% of primary breast carcinomas." (PMID 16168120, 2005).
breast carcinoma (continued). "Moreover, each gene expresses an increased risk genotype (GSTM1 null, GSTT1 null and GSTP1 Val/Val), which may be involved in breast cancer susceptibility when more than one are expressed in each individual." (PMID 32155154, 2020). "Therefore, the GSTP1 Ile105Val genotype could serve as a molecular test to screen for a high risk of breast cancer, to evaluate breast cancer aggressiveness and to predict the efficacy of CTX-based chemotherapy in Chinese populations." (PMID 23826324, 2013). "We speculate that the breast cancer tumors with the GSTP1 105Val variant genotype may have different biological characteristics and responses to CTX-based treatment because of altered enzymatic activity, which may ultimately lead to survival differences of patients." (PMID 23826324, 2013). "In order to test the hypothesis that somatic epigenetic modification in homozygous mutants, combined with reduced enzymatic activity, increases the risk of breast cancer an attempt was made to determine the role of the GSTP1 polymorphism in promoter hypermethylation." (PMID 23226781, 2012). "In addition, the GSTM1 and GSTT1 deletion as well as the GSTP1 rs1138272 variant, were suggested to affect tobacco smoke-related breast cancer risk pointing to the potentially critical role of GSTs in the elimination of exogenous carcinogenic compounds such as polycyclic aromatic hydrocarbons." (PMID 23226154, 2012). "Subgroup analyses showed an association of the GSTT1 gene deletion and the GSTP1 rs947894 variant with HRT-related breast cancer susceptibility (The MARIE-GENICA Consortium on Genetic Susceptibility for Menopausal Hormone Therapy Related Breast Cancer Risk, 2010)." (PMID 23226154, 2012). "Our analysis revealed that mutations in OSRE such as MGST3, GSTP1, NDUFS2, NDUFS8 and PRDX6 were particularly prevalent in breast cancer, and for the five genes the most prevalent genetic alteration was amplification." (PMID 39594421, 2024). "A novel mechanism of GSTP1-1’s action in the development of resistance to adriamycin in breast cancer cells has been established." (PMID 39125992, 2024). "Recently, it was found that the promoter hypermethylation of the GSTP1 gene, along with the RARB gene, which encodes retinoic acid receptor beta, is associated with breast cancer, older age, and postmenopausal Peruvian patients." (PMID 39125992, 2024). "According to alcohol metabolism-involved genes, three were up-regulated (ITGA5, CBS, and SOD2), and six were down-regulated (XDH, XRCC1, MTHFR, CYP1B1, XPC, and GSTP1) among women who died for breast cancer." (PMID 39125744, 2024). "Unique mutations in genes such as NDUFS2, MGST3, PRDX6, NDUFS8, and GSTP1 were found predominantly in breast cancer." (PMID 39594421, 2024). "In other study have also shown that the rs1695 polymorphism in the GSTP1 gene, the GSTM1 null genotype and the GSTT1 null genotype were also associated with an increased incidence of breast cancer." (PMID 37819495, 2023). "Among these, promoter methylation of RARB and GSTP1 genes has shown the potential to be used as breast cancer biomarkers." (PMID 37548362, 2023). "PMR of RARB and GSTP1 genes were obtained from blood plasma cfDNA of 58 breast cancer patients and 58 controls from Oncosalud‐Auna and INEN." (PMID 37548362, 2023). "Abrogating a GSTP1-mediated lactic acid signaling showed attenuated tumor growth and reduced resistance to ROS in breast cancer cells." (PMID 37491277, 2023). "High expression levels of GSTP1 have been reported in relation to tumor growth, drug resistance, and carcinogenesis in colorectal, prostate, and breast cancer." (PMID 37501157, 2023). "In our sample of Peruvian women, breast cancer patients were almost three times more likely to have been exposed to RARB or GSTP1 methylation than controls." (PMID 37548362, 2023). "Tumor suppressor genes like RARB and GSTP1 have been reported as hypermethylated in breast cancer tumors compared with normal tissues in several populations." (PMID 37548362, 2023).
breast carcinoma (continued). "Association between clinicopathological variables of breast cancer patients and promoter methylation ratio (PMR) of the RARB2 + GSTP1 panel." (PMID 37548362, 2023). "Reportedly, glutathione S-transferase pi (GSTP1) is highly expressed in breast cancer, colon cancer, and ovarian cancer and is related with the progression of drug-resistant solid tumor." (PMID 37491277, 2023). "A significant barrier to DNAm study of the GSTP1 gene is its heterogeneous DNAm pattern, which accounts for part of the conflicting discrepancies in the involvement of GSTP1 promoter methylation in breast cancer." (PMID 37901797, 2023). "Methylation of PAX6, GSTP1, RASGRF2, and AKR1B1 promoters has been previously reported to be associated with lymph node metastasis of breast cancer." (PMID 36454866, 2022). "On the contrary, in a Japanese population, breast cancer patients treated with epirubicin and cyclophosphamide, as well as those with the GSTP1 c.313A > G A/A genotype were more likely to develop febrile neutropenia." (PMID 35729577, 2022). "An in vitro study observed glutathione S-transferase pi 1 (GSTP1) promoter demethylated in lycopene-treated MDA-MB-468 breast cancer cells." (PMID 35211240, 2022). "This is the first study in the Hakka population to look at the link between GSTP1 c.313A > G genotypes and clinical toxicity of anthracycline-/paclitaxel-based chemotherapy in breast cancer patients." (PMID 35729577, 2022). "A prominent GST in the resistance formation of breast cancer is GSTP1, which was also observed to be regulated by hsa-miR-200c in the presented experiments." (PMID 36428646, 2022). "In breast cancer, patients with resistance to chemotherapy had higher amounts of GSTP1 than those who responded to the therapy." (PMID 35159299, 2022). "Lok and colleagues proposed a model in which DNICs behave as a “common currency” for NO transport and storage via MRP1 and GSTP1, respectively, in breast cancer cells and also several macrophage models." (PMID 36139130, 2022). "Similar results were observed in breast cancer cells and curcumin-activated GSTP1 expression via antioxidant response element." (PMID 34754622, 2021). "Further, identical correlations were found for GSTM1 and GSTP1 for glioma (n = 153), urothelial cancer (n = 406), ovarian cancer (n = 373), breast cancer (n = 1075), lung cancer (n = 994), and pancreatic cancer (n = 176) patients." (PMID 33946704, 2021). "Knockdown of CLDN6 reduced the expression and the enzyme activity of GSTP1 and increased the cytotoxicity of adriamycin, 5-FU, and cisplatin in ER+ breast cancer cells." (PMID 33946704, 2021). "LAS17 was recently developed as a highly potent and selective GSTP1 inhibitor that impairs breast cancer pathogenicity." (PMID 32526885, 2020). "shRNAs targeting GSTP1 were shown to reduce breast cancer xenograft implants by more than three-fold." (PMID 32526885, 2020). "Three genes were up-regulated (i.e., ITGA5, CBS, and SOD2), while six were down-regulated (i. e, XDH, XRCC1, MTHFR, CYP1B1, XPC, and GSTP1) among individuals who died of breast cancer." (PMID 32078659, 2020). "The GSTP1 gene methylation often shows tumors progression, including breast cancer or unfavorable prognosis." (PMID 32334487, 2020). "An in vitro study observed demethylation of the glutathione S-transferase pi 1 (GSTP1) promoter in lycopene-treated MDA-MB-468 breast cancer cells." (PMID 32917280, 2020). "In two cell studies, lycopene had modest to null effects on DNA methylation of GSTP1, which is involved in prostate and breast cancers." (PMID 31167428, 2019). "The methylation state of GSTP1 is also involved in breast cancer, in fact, the unmethylated state is a benign group while hyper-methylated GSTP1 gene promoters represent a borderline/malignant tumor group of patients." (PMID 31357662, 2019). "In cell studies, lycopene had modest to null effects on DNA methylation of GSTP1, which is involved in prostate and breast cancers." (PMID 31167428, 2019).